RNU6-625P (RNA, U6 small nuclear 625, pseudogene)
Gene: Small nuclear RNA gene on chromosome 17 (78,066,947 to 78,067,053, forward strand). Ensembl gene ENSG00000238658.
Homologues: Orthologues: chimpanzee U6 (100% identical), macaque U6 (82% identical), dog U6 (64% identical), mouse Gm23229 (63% identical). Paralogues in human: RNU6-1131P (83% identical), RNU6-189P (83% identical), RNU6-1011P (82% identical), RNU6-1060P (81% identical), RNU6-1147P (81% identical), RNU6-1243P (81% identical), RNU6-1274P (81% identical), RNU6-1331P (81% identical), RNU6-242P (81% identical), RNU6-266P (81% identical), RNU6-379P (81% identical), RNU6-609P (81% identical), and 1287 more.